RDH5 (retinol dehydrogenase 5)
Diseases named in the same sentence as RDH5 in open-access papers:
RDH5 is named in the same sentence as 46 diseases in open-access papers, as found by Europe PMC text mining. Sharing a sentence is not in itself a finding about the gene and the disease. The quoted sentences say what the papers report.
fundus albipunctatus (7 papers, 2012 to 2024). Fundus albipunctatus is a rare, genetic retinal dystrophy characterized by the presence of numerous small, round, yellowish-white retinal lesions that are distributed throughout the retina but spare the fovea. "Mutations in Rdh5 cause the disease fundus albipunctatus which retards dark adaptation and results in night blindness." (PMID 37714463, 2023). "We identified three variants in RDH5, a novel frameshift deletion Val14CysfsX47, and a haplotype of rare missense variants (Arg228Gln + Tyr237Cys), are responsible for fundus albipunctatus patients in this Chinese family." (PMID 35148716, 2022). "The results of our study further broaden the genetic defects of RDH5 associated with fundus albipunctatus." (PMID 35148716, 2022). "Variants in the RDH5 gene cause autosomal recessive fundus albipunctatus, a rare form of night blindness that is characterized by a delay in the regeneration of cone and rod photopigments." (PMID 35148716, 2022). "We identified novel compound heterozygous variants in RDH5 responsible for fundus albipunctatus in a large Chinese family." (PMID 35148716, 2022). "Variants in RDH5 are associated with fundus albipunctatus and the first identification of clinically significant changes of the RDH5 sequence has been reported in 1999." (PMID 35148716, 2022). "The presumed accumulation of cis-retinol and cis-retinyl esters in the RPE because of 11-cis-retinol dehydrogenase deficiency is responsible for the formation of white flecks in RDH5 mutation-associated fundus albipunctatus." (PMID 23710333, 2013).
cone dystrophy (4 papers, 2012 to 2022). An inherited ocular disorder characterized by the loss of cone cells, the photoreceptors responsible for both central and color vision. "Reported cases in the literature demonstrate that different genetic variants can result in a spectrum of phenotypic presentations of FA, as recent studies have suggested a causal relationship between certain RDH5 genetic variants and cone dystrophy or macular degeneration in addition to nyctalopia." (PMID 35433063, 2022). "We have presented the first reported case of the novel gene variant, c.814_815del (p.Leu272Aspfs∗63), in an individual with FA, which may exist in a subset of RDH5 variants associated with macular atrophy or cone dystrophy." (PMID 35433063, 2022). "Further characterization of the phenotypic correlation of different RDH5 variants would be helpful in identifying and counseling the subset of patients that are genetically predisposed to developing early-onset macular atrophy or cone dystrophy." (PMID 35433063, 2022). "Thus, the identification of RDH5 variants with a higher probability of resultant macular degeneration or cone dystrophy in FA patients is valuable in clinical practice as we provide patients with individualized prognostic information on potential vision loss based on their genotype." (PMID 35433063, 2022).
myopia (4 papers, 2013 to 2023). "The specific SNP in RDH5 has previous associations with a number of ophthalmic phenotypes including the age one started wearing glasses, cataract and myopia." (PMID 36848389, 2023). "Co-localizations of fRPE e/sQTLs with age-related macular degeneration (AMD) and myopia GWAS data suggest new candidate genes, and mechanisms by which a common RDH5 allele contributes to both increased AMD risk and decreased myopia risk." (PMID 31123710, 2019). "More puzzling is the relationship between lower RDH5 transcript levels (and presumably enzyme activity) and a reduced risk of myopia." (PMID 31123710, 2019). "Co-localization of the same RDH5 e/sQTL with both AMD and myopia GWAS loci suggests risk mechanisms for these very different complex diseases." (PMID 31123710, 2019).
retinal degeneration (4 papers, 2020 to 2024). Degeneration of the retina. "The results from the present study suggest that although it is difficult to detect qualitative abnormalities, SD-OCT can detect quantitative changes in photoreceptors even in the early stage of retinal degeneration induced by the Rdh5 gene mutation in mice." (PMID 32271812, 2020). "Overall, our results showed significant enrichment for positively selected genes involved in sensory perception development during sheep domestication; RDH5 and its variants may be related to the retinal degeneration in sheep." (PMID 37384328, 2023). "In RPE, several proteins associated with retinal degeneration were downregulated (e.g., TIMP3, RDH5, PRELP)." (PMID 38605034, 2024). "However, Rdh5 knockout (Rdh5-/-) mice reportedly do not show the typical white dots and retinal degeneration as in humans." (PMID 32271812, 2020).
congenital stationary night blindness (3 papers, 2014 to 2024). "Six genes encoding major components of the phototransduction cascade (RHO, GNAT1, PDE6B, GRK1, and SAG) and the regeneration of the visual pigment (RDH5) are described in congenital stationary night blindness (CSNB) patients." (PMID 24760071, 2014).
Leber congenital amaurosis (3 papers, 2017 to 2025). Leber congenital amaurosis (LCA) is a retinal dystrophy defined by blindness and responses to electrophysiological stimulation (Ganzfeld electroretinogram (ERG)) below threshold, associated with severe visual impairment within the first year of life. "Mutations in LRAT or RPE65 are associated with Leber congenital amaurosis, and variants in RDH5 lead to fundus albipunctatus." (PMID 40365019, 2025). "Although variations in RDH14 are benign and not disease causing, mutations in RDH5 and RDH12 are known to be associated with fundus albipunctatus and leber congenital amaurosis." (PMID 28450823, 2017).
night blindness (3 papers, 2015 to 2023). Inability to see clearly in dim light. "We present a novel pathogenic RDH5 gene mutation in a 16-year-old female patient with symptoms of night blindness." (PMID 25820994, 2015).
retinal disease (3 papers, 2010 to 2024). "Moreover, we have presented the first molecular evidence for 11-cis retinol dehydrogenase 5 (RDH5) gene mutation in a Polish patient with this rare retinal disease." (PMID 25820994, 2015). "known retinal disease genes (BEST1 [NM_004183], C1QTNF5 [NM_015645], CDH3 [NM_001793], LRAT [NM_004744], RDH5 [NM_002905], RDH11 [NM_016026], RGR [NM_002921], RLBP1 [NM_000326] and STRA6 [NM_022369])." (PMID 20479888, 2010).
retinitis pigmentosa (3 papers, 2016 to 2024). Retinitis pigmentosa (RP) is an inherited retinal dystrophy leading to progressive loss of the photoreceptors and retinal pigment epithelium and resulting in blindness usually after several decades. "Evaluating the effectiveness of transplantation can lay the foundation for the development of new treatments for these diseases, including retinitis pigmentosa with RPE-related gene abnormalities (such as RPE65, RDH5, and MERTK), AMD with RPE atrophy." (PMID 33923985, 2021).
colorectal cancer (2 papers, 2020 to 2023). A primary or metastatic malignant neoplasm that affects the colon or rectum. "ADH1B, ADH1C, RDHL, and RDH5 mRNAs were decreased in colorectal cancer samples, and expression of ADH1B and ADH1C mRNAs decreased regarding progression from adenoma to early and more advanced colorectal cancer." (PMID 37569466, 2023). "In colorectal carcinoma, RDH5 was significantly decreased in the mRNA level, leading to diminished all-trans-retinoic acid biosynthesis and thus contributing to the progression of colorectal cancer by affecting cell growth and differentiation." (PMID 32788868, 2020).
retinal dystrophies (2 papers, 2022 to 2024). "Furthermore, 24 families had VUS, two families with variants in genes related to non-syndromic EoHM (SCO2 and ZNF644) and seven families with variants in genes associated with other retinal dystrophies (TRPM1, CACNA1F, KCNV2, RDH5 and MERTK)." (PMID 35457050, 2022).
thyroid cancer (2 papers, 2020). "Among the four methylation-driven genes, the high expression level of TREM1, BIRC7, and SLC26A7 prognosticated low survival rate, whereas RDH5 acted as protective genes to suggest good prognosis of thyroid cancer." (PMID 32296463, 2020).
adenoma (1 paper, 2023). A neoplasm arising from the epithelium. "Comparison of benign colon adenomas, colon cancer, and normal colon tissue by microarray and RT-PCR analyses revealed reduced expression of the genes RDHL and RDH5 in adenoma and cancer samples." (PMID 37569466, 2023).
arterial disorder (1 paper, 2023). An impairment of the structure or function of the blood vessels which carry blood away from the heart. "Those SNPs located at RDH5/ORMLD2 and AGPAT3 genes also have a strong effect on multiple ocular traits and diseases (such as macular thickness and retinal detachment), hypertension, and arterial disorders." (PMID 37188768, 2023).
autosomal recessive cone-rod dystrophies (1 paper, 2008). "Seven genes reported to be associated with autosomal recessive cone-rod dystrophies (crd), ABCA4, RDH5, CORD8, CORD9, RPGRIP1, CRX and GUCY2D were therefore included in the study." (PMID 18593457, 2008).
breast carcinoma (1 paper, 2021). "Furthermore, we generated an expression risk score for each of the breast cancer patients in the METABRIC Discovery, Validation and TCGA sets using the seven genes RDH5, RDH8, RDH10, RDH11, RDH12, RDH13, RDH14." (PMID 33436820, 2021). "To explore the expression patterns of the seven genes RDH5, RDH8, RDH10, RDH11, RDH12, RDH13, RDH14 in normal tissues as well as breast cancer tissue, we first drew a heat map of the expression levels of the genes across normal human tissues from GTEx portal." (PMID 33436820, 2021).
Bull's eye maculopathy (1 paper, 2024). Progressive maculopathy characterized by concentric regions of hyper- and hypopigmentation, with an initial foveal sparing and whose appearance is said to resemble the central target of a dart board. "Pathogenic variants in the RDH5 gene are the most common cause of fundus albipunctatus, which may be accompanied by macular dystrophy, bull’s eye maculopathy, photophobia, and RPE degeneration." (PMID 39858579, 2024).
cone-rod dystrophy (1 paper, 2008). Inherited retinal dystrophies that belong to the group of pigmentary retinopathies. "The genes involved in cone degeneration, CNGB3, CNGA3 and GNAT2, and the genes involved in cone-rod dystrophy, ABCA4, RDH5, Cord8, Cord9, RPGRIP1, GUCY2D and CRX, were all excluded from being involved in the cone-rod dystrophy described in this family of SWHD." (PMID 18593457, 2008). "Three of the genes, CNGB3, CNGA3 and GNAT2, involved in cone degeneration and seven genes and loci, ABCA4, RDH5, CORD8, CORD9, RPGRIP1, GUCY2D and CRX, reported to be involved in cone-rod dystrophies were studied." (PMID 18593457, 2008).
glioma (1 paper, 2024). A benign or malignant brain and spinal cord tumor that arises from glial cells (astrocytes, oligodendrocytes, ependymal cells). "After that, we found that 6 immune checkpoints (CD274, CTLA4, LAG3, LGALS9, PDCD1, and PDCD1LG2) were significantly upregulated in the high-glioma-risk group, while RDH5, RDH10 and DHRS3 simultaneously have a substantial positive connection with PDCD1LG2." (PMID 39465792, 2024). "ADH4, DHRS3, LRAT, RDH10, RDH12, and RDH5 were higher expressed in the high-glioma-risk group while DHRS9 was lower expressed." (PMID 39465792, 2024). "We identified 7 promising prognostic genes (ADH4, DHRS3, DHRS9, LRAT, RDH10, RDH12, and RDH5) within glioma and developed a prognostic model with significant predictive accuracy." (PMID 39465792, 2024). "Ultimately, ADH4, DHRS3, DHRS9, LRAT, RDH10, RDH12, and RDH5 were selected as prognostic genes for building an RA metabolism–related prognostic signature with glioma." (PMID 39465792, 2024). "The prognostic signature comprised of ADH4, DHRS3, DHRS9, LRAT, RDH10, RDH12, and RDH5 based on RA metabolism was established, which provided a theoretical basis and reference value for the research of glioma." (PMID 39465792, 2024).
hepatocellular carcinoma (1 paper, 2020). A malignant tumor that arises from hepatocytes. "RDH5 was significantly downregulated in hepatocellular carcinoma tissues, and low RDH5 expression was associated with metastasis and poor patient prognosis." (PMID 32788868, 2020). "In our analysis, the expression of RDH5 was also associated with the clinicopathological feature of metastasis of hepatocellular carcinoma." (PMID 32788868, 2020). "First, low RDH5 expression was associated with metastasis in hepatocellular carcinoma tissues." (PMID 32788868, 2020). "Univariate Cox analysis demonstrated that new neoplasm, M stage, N stage, T stage (T3 and T4), tumor invasion, clinical stage (III-IV), and lower RDH5 expression can play prognostic roles in overall survival in hepatocellular carcinoma." (PMID 32788868, 2020). "The univariate analysis showed that seven factors, including new neoplasms, M stage, N stage, T stage (T3 and T4), tumor invasion, clinical stage (III-IV), and lower RDH5 expression were poor prognostic factors for OS in hepatocellular carcinoma patients." (PMID 32788868, 2020). "This study is the first time to indicate that DNA methylation affects RDH5 expression in hepatocellular carcinoma." (PMID 32788868, 2020). "In our study, we provided the first evidence that RDH5 plays a crucial role in suppressing proliferation and metastasis, and the RDH5 promoter is methylated in hepatocellular carcinoma." (PMID 32788868, 2020). "The multivariate Cox analysis confirmed that RDH5 expression, M stage, and clinical-stage play independent prognostic roles in overall survival in hepatocellular carcinoma." (PMID 32788868, 2020). "The increase of RDH5 expression after treatment with DAC was consistent with the baseline DNA methylation levels in the Hepatocellular carcinoma cell line." (PMID 32788868, 2020). "Collectively, our research showed that RDH5 was dysregulated in hepatocellular carcinoma patients, and this dysregulation can indicate a worse prognosis." (PMID 32788868, 2020). "In summary, our study is the first to elucidate the critical roles of RDH5 in regulating the HIPPO/YAP signaling pathway in hepatocellular carcinoma." (PMID 32788868, 2020). "In our research, we first showed that low expression of RDH5 in hepatocellular carcinoma could activate the Hippo/YAP signaling pathway and promote YAP translocation into the nucleus." (PMID 32788868, 2020). "Protein expression was visualized by immunofluorescence, which shown that downregulating RDH5 in DEN and CCL4 induced-mouse hepatocellular carcinoma." (PMID 32788868, 2020). "We examined the mRNA level of RDH5 by using q-PCR in hepatocellular carcinoma (HCC) and adjacent non-cancerous tissues." (PMID 32788868, 2020).
Hyperglycemia (1 paper, 2018). An increased concentration of glucose in the blood. "This compound neutralized the hyperglycemia-elicited reduction of the retinoid visual cycle components of RPE65, LRAT, RDH5, CRBP, CRALBP, IRBP, and STRA6 in retina." (PMID 30096827, 2018).
papillary thyroid carcinoma (1 paper, 2020). "Pyrosequencing and RT-PCR showed that the RDH5 gene is hypomethylated and overexpressed in papillary thyroid carcinoma tissues compared with matched non-neoplastic adjacent tissues, indicating that DNA methylation may regulate the expression of the RDH5 gene." (PMID 32788868, 2020).
refractive error (1 paper, 2024). A defect in the focusing of light on the retina as in astigmatism, myopia, or hyperopia. "In addition, genes associated with photoreceptor function and phototransduction, such as Vsx1 and Rdh5, were changing in chick retinas and are also implicated in refractive errors in humans." (PMID 39876870, 2024).
retinitis punctata albescens (1 paper, 2022). "Thus, the incorporation of genetic testing in identifying RDH5 gene variants has facilitated the accurate diagnosis of FA in patients whose phenotypic presentation can be clinically confused with other flecked retina syndromes such as retinitis punctata albescens." (PMID 35433063, 2022).
Stargardt disease (1 paper, 2020). "There are several important instances where laboratory rodent engineered models fail to recapitulate the human disease; important examples including ABCA4-Stargardt disease, RDH5-retinopathy, or where the gene involved is not present in the mouse or rat genome e.g., EYS." (PMID 32260251, 2020).
Strabismus (1 paper, 2008). A misalignment of the eyes so that the visual axes deviate from bifoveal fixation. "Mutations causing strabismus have not yet been reported, but related genes such as RDH5 and RDH12 were shown to cause fundus albipunctatus and retinal dystrophy in human, which can be accompanied by strabismus." (PMID 18836565, 2008).
cancer (4 papers, 2013 to 2021). A tumor composed of atypical neoplastic, often pleomorphic cells that invade other tissues. "Some reports have demonstrated RDH5 was dysregulated in many different cancers." (PMID 32788868, 2020).
retinopathy (4 papers, 2018 to 2024). "Dark-adapted red flash ERGs aid diagnosis of rod- and S-cone monochromacy, cone dystrophy, vitamin A deficiency, RDH5-retinopathy, SAG- or GRK1-retinopathy, some cases of rod-cone dystrophy, RGS9- and R9AP-retinopathy and colour vision deficiencies." (PMID 34045684, 2021). "This occurs, for example, in vitamin A deficiency, fundus albipunctatus (RDH5-retinopathy) and Oguchi disease (SAG- or GRK1-retinopathy) and in some cases of rod-cone dystrophy including early stages of Bothnia dystrophy (RLBP1-retinopathy)." (PMID 29934801, 2018). "The Rdh5-mutant cat promises to be a valuable model because the Rdh5−/− mouse lacks a phenotype and does not recapitulate RDH5-retinopathy in human patients." (PMID 32260251, 2020).
tumor (4 papers, 2013 to 2024). "Similar results from the TCGA database was shown that the expression of RDH5 was significantly downregulated in tumor tissues (p<0.001), with an area under the curve of 0.8864 (n=422)." (PMID 32788868, 2020). "However, the role of RDH5 in tumor prognosis is still unclear." (PMID 32788868, 2020). "Results show that leptin signaling increases the expression of tumor progression and chemoresistance-related genes (ABCB1, WNT4, ADHFE1, TBC1D3, LL22NC03, RDH5, ITGB3) in TNBC cells." (PMID 32471192, 2020).
RDH5 also shares sentences with these, for which no sentence is quoted: achromatopsia (1 paper); age-related macular degeneration (1); albinism (1); diabetes (1); gastric cancer (1); Glucose intolerance (1); Hypertension (1); Insulin resistance (1); kidney disease (1); macular degeneration (1); Macular dystrophy (1); microphthalmia (1); oligocone trichromacy (1); Photophobia (1); retinal detachment (1); triple-negative breast carcinoma (1); Usher syndrome (1).